MACC1 (MET transcriptional regulator MACC1)
Diseases named in the same sentence as MACC1 in open-access papers (continued):
Sharing a sentence is not in itself a finding about the gene and the disease.
ovarian carcinoma (continued). "The downregulation of MACC1 also decreased phosphorylated (p)ERK1/2 and BCL2 protein levels and upregulated the expression levels of BAD and BAX, making the ovarian cancer cells sensitive towards cisplatin treatment." (PMID 39580452, 2024). "MACC1 expression has been shown to correlate with PIM3 expression and overexpression of PIM3 in ovary cancer cells increased MACC1 mRNA and protein expression." (PMID 33946744, 2021). "For example, miR-338-3p suppresses the metastasis of ovarian carcinoma cell through suppressing proliferation and epithelial-mesenchymal transition (EMT) enhanced by MET Transcriptional Regulator MACC1 (MACC1)." (PMID 32976115, 2020). "In the present liquid biopsy approach, we systematically analyzed clinical relevance of circulating MACC1 and S100A4 transcripts in ovarian cancer patients." (PMID 30927479, 2019). "We observed that serum levels of both, MACC1 and S100A4, are significantly upregulated at primary diagnosis of ovarian cancer, compared to healthy controls." (PMID 30927479, 2019). "MACC1 and S100A4 transcripts were significantly elevated in serum of ovarian cancer patients, compared to healthy controls (P = 0.024; P < 0.001)." (PMID 30927479, 2019). "MACC1 and S100A4 transcripts were quantified in a total of 318 serum samples from 79 ovarian cancer patients by RT‐qPCR and digital droplet PCR, respectively." (PMID 30927479, 2019). "Conclusively, circulating MACC1 and S100A4 transcripts are significantly elevated in serum of ovarian cancer patients and show a high correlation in the course of surgery and chemotherapy, which is mostly independent from CA125 serum levels." (PMID 30927479, 2019). "Compared to MACC1, S100A4 levels allow superior discrimination between ovarian cancer patients and healthy controls." (PMID 30927479, 2019). "Nevertheless, despite a very recent preliminary study, investigating clinical relevance of S100A4 protein in serum, this is the first study on MACC1 and S100A4 serum transcripts in ovarian cancer." (PMID 30927479, 2019). "Collectively, high circulating MACC1 and S100A4 levels in serum of ovarian cancer patients correlate with advanced disease and predict suboptimal primary debulking surgery without achieving macroscopically complete tumor resection." (PMID 30927479, 2019). "In contrast to MACC1, S100A4 levels in serum of ovarian cancer patients showed only a small overlap to healthy controls, resulting in a good discrimination between ‘ovarian cancer’ and ‘healthy’ (AUC = 0.81)." (PMID 30927479, 2019). "Our data harmonize with the previously shown oncogenic and metastasis‐initiating impact of MACC1 and S100A4 and extend our knowledge of these genes to innovative liquid biopsy approaches for ovarian cancer." (PMID 30927479, 2019). "We encourage further investigation, considering MACC1 and S100A4 as a potential therapeutic target for ovarian cancer." (PMID 30927479, 2019). "For the first time, we systematically tracked circulating serum levels of MACC1 and S100A4 transcripts in the course of surgery and chemotherapy and analyzed their clinical relevance for ovarian cancer." (PMID 30927479, 2019). "We analyzed the levels of serum MACC1 and S100A4 transcripts in a cohort of clinically documented ovarian cancer patients at primary diagnosis (n = 77) and compared it to the levels in serum of healthy controls (n = 25)." (PMID 30927479, 2019). "Thus, knockdown of MACC1 by RNAi could inhibit the growth of ovarian carcinoma cells." (PMID 21923915, 2011). "Our data now extend our knowledge on MACC1 and S100A4 to ovarian cancer." (PMID 30927479, 2019). "Furthermore, we encourage future translational investigations with MACC1 and S100A4 as therapeutic targets for ovarian cancer." (PMID 30927479, 2019). "Oncogenic function of MACC1 and S100A4 has likewise been proposed for ovarian cancer." (PMID 30927479, 2019).
ovarian carcinoma (continued). "Therefore, the highly concordant dynamics of MACC1 and S100A4 transcripts in serum of ovarian cancer patients could be explained by a proportional release upon apoptosis or by a possibly co‐regulated active secretion." (PMID 30927479, 2019). "However, clinical relevance of MACC1 and S100A4 transcripts as potential blood‐based biomarkers for ovarian cancer patients is completely unknown." (PMID 30927479, 2019). "Since we found that levels of MACC1 and S100A4 transcripts at primary diagnosis correlated with FIGO stage, we suggest that a significant proportion of MACC1 and S100A4 transcripts is derived from ovarian cancer cells and reflects the patient's individual tumor load." (PMID 30927479, 2019). "However, the exact survival effect of MACC1 on epithelial ovarian cancer (EOC) patients has not yet been established." (PMID 30515418, 2018). "However, the high expression of MACC1 mRNA was not statistically significant in 44 patients with endometrioid cancer and in 115 patients with stage I or II ovarian cancer patients." (PMID 30515418, 2018). "However, the relations between abnormal expression of MACC1 and ovarian carcinoma had not yet been reported." (PMID 21923915, 2011). "We conclude that high levels of circulating MACC1 or S100A4 transcripts at primary diagnosis (but not among follow‐up samples during surgery and adjuvant chemotherapy) are unfavorable prognostic factors for ovarian cancer patients and indicate poor prognosis." (PMID 30927479, 2019).
hepatocellular carcinoma (26 papers, 2011 to 2025). A malignant tumor that arises from hepatocytes. "MACC1 increased the Warburg effect via elevated expression of key glycolytic enzymes in gastric and hepatocellular cancers, which is linked to trastuzumab resistance due to increased PI3K/AKT signaling." (PMID 33652667, 2021). "Knockdown of metastasis-associated in colon cancer 1(MACC1) expression using shRNA reduced hepatocellular carcinoma Huh7 cell migration and invasion abilities, which were associated with the downregulation of MMP-9 protein." (PMID 24476461, 2014). "There is evidence that MACC1 overexpression predicts a poor clinical outcome of hepatitis B virus-related hepatocellular carcinoma." (PMID 40361484, 2025). "Increased PTEN expression was found after MACC1 silencing in esophageal carcinoma, and in hepatocellular carcinoma, MACC1 induced PI3K activation." (PMID 37051546, 2023). "In hepatocellular carcinoma, miR-195-5p targets MACC1 to block cell multiplication, migration, and invasion." (PMID 34308761, 2021). "MACC1 inhibits the cell apoptosis by targeting the HGF/c-MET/PI3K/AKT signaling pathway in hepatocellular carcinoma." (PMID 28348518, 2017). "The predictive value of MACC1 for therapy response was demonstrated in rectal, pancreatic, and advanced hepatocellular cancer." (PMID 25884643, 2015). "The positive rate of MACC1 protein expression is related to the protein expression c-Met as shown by QRT-PCR in primary hepatocellular carcinoma and is closely related to recurrence and disease-free survival." (PMID 24325214, 2013). "MACC1 plays a key role in the transition from adenoma to carcinoma in mice and humans and has also been identified as a metastatic and prognostic biomarker for other solid tumors, such as hepatocellular carcinoma, lung cancer, and breast cancer." (PMID 36545127, 2022). "In hepatocellular carcinoma, MACC1 is considered to be a biomarker of survival prognosis." (PMID 33712897, 2021). "MiR-200a suppresses cell growth and migration by targeting MACC1 in hepatocellular carcinoma." (PMID 28403886, 2017). "MACC1 expression is significantly related to vascular invasion and alpha-fetoprotein level, which might serve as a novel prognostic marker in hepatocellular carcinoma." (PMID 24325214, 2013). "However, the value of MACC1 as a potential biomarker for hepatocellular carcinoma (HCC) remains unknown." (PMID 21955323, 2011). "The aim of this study was to investigate the prognostic value of MACC1 in early-stage and AFP-normal hepatocellular carcinoma (HCC)." (PMID 23717574, 2013). "RT-PCR showed that there was a lack of MACC1 expression in the normal liver cell line L-02, while all of four hepatoma cell lines (SMMC-7721, Hep-G2, MHCC-97L and MHCC-97H) expressed MACC1 mRNA." (PMID 21955323, 2011). "Data showed that there was a lack of MACC1 expression in the normal liver cell line L-02, while all of three hepatoma cell lines (HepG2, MHCC-97L and MHCC-97H) expressed MACC1." (PMID 23414367, 2013). "MACC1 is more frequently expressed in vascular invasive hepatocellular carcinoma and a valuable indicator for stratifying the prognosis of TNM stage I patients with hepatocellular carcinoma." (PMID 23573286, 2013).
breast carcinoma (24 papers, 2013 to 2025). "The metastasis-associated colon cancer-1 (MACC1) gene was reported as a reliable biomarker for early detection of metastasis and prediction of prognosis of breast cancer." (PMID 34577857, 2021). "The current study is one of the initial study to evaluate the diagnostic and prognostic value of novel serum MACC-1 marker in breast cancer patients." (PMID 33400729, 2020). "This study is conducted to evaluate the serum MACC-1 level as a diagnostic marker for breast cancer (BC)." (PMID 33400729, 2020). "This study is therefore conducted to evaluate the serum MACC-1 level as a diagnostic marker for breast cancer." (PMID 33400729, 2020). "Increased serum MACC1 was associated with breast cancer TNM stage (P < 0.001), tumor size (P < 0.001), lymph node metastasis (P < 0.001), and Ki-67 status (P = 0.014)." (PMID 27793048, 2016). "The aim of our study was to determine the diagnostic and prognostic value of preoperative serum MACC1 levels in breast cancer patients." (PMID 27793048, 2016). "The current study represents the first demonstration of an association between MACC1 expression and breast cancer survival and the value of MACC1 as a prognostic marker for the disease." (PMID 23497677, 2013). "The molecular pathways underlying a possible biological role of MACC1 in breast cancer progression are yet to be elucidated." (PMID 23497677, 2013). "Among the 154 breast cancer cases with positive ER status in cohort 1, high expression MACC1 was significantly associated with relapse-free survival (P = 0.003, left)." (PMID 23497677, 2013). "The prognostic role of the expression of metastasis-associated in colon cancer-1 (MACC1) in gynecologic cancers and breast cancer remains unclear." (PMID 33663046, 2021). "On the other hand, for MACC1 SNP rs4721888, the frequency of rs4721888 GC and GC+CC variants was higher compared with the rs4721888 CC genotype in breast cancer patients, suggesting that the rs4721888 polymorphisms in MACC1 is associated with the risk of breast cancer susceptibility." (PMID 32047570, 2020). "In patients with human epidermal growth factor 2 (HER2)-positive breast cancer, the MACC1 SNPs rs1990172, rs975263, and rs3735615 were associated with clinical outcome such as increased risk for progression or death and a significant protective impact on event-free survival and overall survival." (PMID 32047570, 2020). "Our findings demonstrated that circulating MACC1 could serve as a reliable diagnostic and prognostic biomarker for breast cancer." (PMID 27793048, 2016). "We performed siRNA-based silencing of Macc1 in the aggressive T1 cells in order to evaluate the role of Macc1 gene expression in breast cancer cell proliferation." (PMID 37841442, 2023). "High expression of MACC1 was significantly associated with shorter RFS/PFS/DFS in gynecologic cancers and breast cancer (HR = 2.37, 95%CI = 1.44–3.90, P < .01)." (PMID 33663046, 2021). "The aim of this systematic review and meta-analysis was to determine the prognostic significance of MACC1 expression in gynecologic cancers and breast cancer." (PMID 33663046, 2021). "This study investigated the prognostic significance of MACC1 in breast cancer in relation to the clinicopathologic characteristics and patients’ survival." (PMID 34577857, 2021). "After we interrupting the function of MACC1, and breast cancer cells triggered the apoptosis pathway and regained sensitivity to ionizing radiation." (PMID 34221989, 2021). "It is also difficult to adopt the results of MACC1 expression in breast cancer subtypes, particularly TNBC, given the relatively small number of TNBC cases in this study." (PMID 34577857, 2021). "In conclusion, the present results suggested that the FGD5-AS1/miR-497/MACC1 axis contributed to radiation resistance in breast cancer." (PMID 34221989, 2021).
breast carcinoma (continued). "High expression of MACC1 is associated with worse tumor differentiation, more advanced FIGO stage and earlier lymph node metastasis in gynecologic cancers and breast cancer." (PMID 33663046, 2021). "Multicenter prospective trials with large sample size and long follow-up period should be carried out to determine the prognostic value of MACC1 expression in gynecologic cancers and breast cancer in future." (PMID 33663046, 2021). "Compared to low expression of MACC1, high expression of MACC1 predicts a worse prognosis of gynecologic cancers and breast cancer." (PMID 33663046, 2021). "The expression of MACC1 can serve as a prognostic indicator of gynecologic cancers and breast cancer." (PMID 33663046, 2021). "The subgroup analysis also showed high expression of MACC1 was an unfavorable prognostic factor of gynecologic cancers and breast cancer (P < .05)." (PMID 33663046, 2021). "Studies focusing on the relationship between the expression of MACC1 and prognosis in gynecologic cancers and breast cancer were included into the analysis." (PMID 33663046, 2021). "First, to our knowledge, we are first to evaluate the prognostic value of MACC1 expression in gynecologic cancers and breast cancer in the form of systematic review and meta-analysis." (PMID 33663046, 2021). "High expression of MACC1 predicts shorter OS and RFS compared to low MACC1 expression in gynecologic cancers and breast cancer." (PMID 33663046, 2021). "In this study, serum MACC-1 levels were significantly elevated (p < 0.0001) in breast cancer patients compared to the control group." (PMID 33400729, 2020). "The mean serum MACC-1 level in breast cancer patients was 3.46 ± 1.3 ng/ml which was significantly higher than control subjects mean serum MACC-1 level (1.90 ± 0.2 ng/ml) (p < 0.0001)." (PMID 33400729, 2020). "This study showed that serum MACC-1 can be a potential biomarker for diagnosis and tumor progression in patients with breast cancer." (PMID 33400729, 2020). "In breast cancer, when estrogen receptor (ER) status were stratified, MACC1 was of prognostic value for both ER-negative and ER-positive patients." (PMID 30805302, 2019). "Other than CRC, as it has been investigated, the prognostic value of MACC1 has been further proved in other malignancies such as hepatocellular cancer, ovarian cancer and breast cancer." (PMID 30805302, 2019). "Serum MACC1 levels were measured in 378 breast cancer patients, 120 patients with benign breast disease, and 40 healthy volunteers using an ELISA." (PMID 27793048, 2016). "Serum MACC1 measurement successfully discriminated breast cancer patients from normal and healthy controls (AUC = 0.785, 95% CI: 0.746–0.825) with an optimal cut-off value of 38.35 pg/ml (sensitivity = 0.725, specificity = 0.696)." (PMID 27793048, 2016). "It was reported that single nucleotide polymorphism (SNP) of metastasis-associated in colon cancer-1 (MACC1) gene, a key regulator of the HGF/MET pathway, was significantly associated with clinical outcome in HER2 positive breast cancer." (PMID 27650797, 2016). "Serum MACC1 levels were higher in breast cancer patients than patients with benign disease or healthy volunteers." (PMID 27793048, 2016). "Metastasis-associated in colon cancer-1 (MACC1) was found overexpressed by Western blot and immunohistochemistry in breast cancer tissues." (PMID 24550697, 2014). "Toward this end, further investigation on the mechanism by which MACC1 is involved in the development and progression of breast cancer and prospective studies on the prognostic significance of MACC1 are needed." (PMID 23497677, 2013). "MACC1 protein expression was analyzed in two cohorts of clinicopathologically characterized breast cancer using immunohistochemistry." (PMID 23497677, 2013). "In the present study, we analyzed for the first time the expression of MACC1 in breast cancer and its correlation with clinicopathologic features, including metastasis and patient survival." (PMID 23497677, 2013).